YWHAZP10 (YWHAZ pseudogene 10)
Gene: Processed pseudogene on chromosome X (41,675,760 to 41,676,494, reverse strand). Ensembl gene ENSG00000217624.
Diseases named in the same sentence as YWHAZP10 in open-access papers:
YWHAZP10 is named in the same sentence as 5 diseases in open-access papers, as found by Europe PMC text mining. Sharing a sentence is not in itself a finding about the gene and the disease. The quoted sentences say what the papers report.
juvenile idiopathic arthritis (1 paper, 2024). Juvenile idiopathic arthritis (JIA) is the term used to describe a group of inflammatory articular disorders of unknown cause that begin before the age of 16 and last over 6 weeks. "Additionally, YWHAZP2, YWHAZP3, and YWHAZP10 expression is elevated in a study of LPS-treated PBMC of juvenile idiopathic arthritis patients." (PMID 38674334, 2024).
psoriatic arthritis (1 paper, 2024). Joint inflammation associated with psoriasis. "A study of T cells from the blood and synovial fluid of psoriatic arthritis patients revealed the expression of YWHAZP3 and YWHAZP10 in both leukocytes and T cells; the expression of YWHAZP1, YWHAZP5, and YWHAZP6 in leukocytes only; the expression of YWHAZP2 in T Cells only." (PMID 38674334, 2024).
rheumatoid arthritis (1 paper, 2024). A chronic, systemic autoimmune disorder characterized by inflammation in the synovial membranes and articular surfaces. "Similarly, synovial tissue macrophages from patients in remission from rheumatoid arthritis showed the expression of YWHAZP3, YWHAZP4, and YWHAZP10." (PMID 38674334, 2024).
tumor (1 paper, 2024). "Decreased expression of YWHAZP7 and YWHAZP10 in the platelets of six different tumor tissues is also reported." (PMID 38674334, 2024).
YWHAZP10 also shares sentences with these, for which no sentence is quoted: autoimmune thrombocytopenia (1 paper).